ACSL4 (acyl-CoA synthetase long chain family member 4)
Diseases named in the same sentence as ACSL4 in open-access papers (continued):
Sharing a sentence is not in itself a finding about the gene and the disease.
breast cancer (continued). "Research has shown ACSL4 is preferentially expressed in basal-like breast cancer cell lines, promoting ferroptosis, while it is often silenced in most luminal-type breast cancer cell lines that are resistant to ferroptosis, suggesting that ACSL4 determines ferroptosis sensitivity in breast cancer." (PMID 35743814, 2022). "Notably, all the FA metabolic genes ELOVL6, ACSL1, ACSL3, ACSL4, ACDSB and ACAT1 showed significant positive correlation with NAT10 suggesting that overexpression of NAT10 in breast cancer patients is associated with FA metabolism." (PMID 36149760, 2022). "In addition, ACSL4 may be an effective therapeutic target for the regulation of multiple transporters associated with anti-cancer resistance through the mammalian target of rapamycin (mTOR) pathway, thereby restoring drug sensitivity in breast cancer with poor prognosis." (PMID 35910359, 2022). "Interestingly, ACSL4 was found be negatively correlated with Ki-67 expression in breast cancer patients." (PMID 35910359, 2022). "Specifically, they found overexpressing ACSL4 reduces the cytotoxic effect of tamoxifen in MCF-7 and SKBr-3, suggesting inhibiting ACSL4 could overcome tamoxifen resistance in breast cancer." (PMID 35448537, 2022). "ACSL4 have been well established as the positive regulator of ferroptosis and could be served as a novel predictive/prognostic breast cancer biomarker." (PMID 35910359, 2022). "Since ACSL4 is expressed higher in breast cancer compared to the adjacent normal tissue, and PUFAs are targets of lipid peroxidation, cancer cells might be more susceptible to lipid peroxidation and ferroptosis, thus GPX4 is more essential in cancer cells." (PMID 33672555, 2021). "Furthermore, online UALCAN analysis and Kaplan-Meier Plotter analysis show a correlation between ACSL4 expression and breast cancer prognosis." (PMID 34040532, 2021). "Increased ACSL4 expression is a determinant of drug resistance in metastatic breast cancer cells where altered cellular energetics leads to increased expression of the ATP-binding cassette (ABC) transporter, which mediates the egress of chemotherapeutic molecules." (PMID 32286604, 2020). "The expression of ACSL4 in breast cancer tissues has been inconsistent in different studies." (PMID 33292585, 2020). "Using RNA-seq and functional proteomics, we have reported that the single overexpression of ACSL4 in breast cancer cells of low aggressiveness regulates a broad spectrum of signaling pathways involved in both tumorigenesis and resistance to conventional treatments." (PMID 31311992, 2019). "Interestingly, the role of ACSL4 in sensitizing to ferroptosis has also been confirmed in basal-like breast cancer cell lines." (PMID 31344914, 2019). "In breast cancer, another ACSL4-mediated resistance mechanism has been shown." (PMID 31344914, 2019). "In this scenario, the current work analyzes the mechanisms underlying the differential regulation of ACSL4 in TNBC and ERα-positive breast cancer cells, which may allow to identify therapeutic targets and possible future drug combinations." (PMID 31311992, 2019). "Moreover, mTORC1 inhibition abrogates the ACSL4-mediated chemotherapy resistance in breast cancer cells." (PMID 31344914, 2019). "ACSL4, a regulator of fatty acid oxidation or lipid biosynthesis, was identified recently as a biomarker of sensitivity to ferroptosis preferentially expressed in basal-like breast cancer cell lines but also found to be elevated in HER2+ve SKBR3 cells." (PMID 31409375, 2019). "With respect to malignant transformation, ACSL4 is overexpressed in hepatocellular carcinoma as well as in colon adenocarcinoma, and has been demonstrated to play a role in the more aggressive forms of breast cancer." (PMID 28412757, 2017). "However, the results of the current analysis are inconsistent with a previous study investigating the overexpressed ACSL4 in breast cancer tissue." (PMID 27171439, 2016).
breast cancer (continued). "Previous work from our laboratory has demonstrated an inverse relationship between the expression of ACSL4 and AR/ER in breast cancer cell lines and tissue samples; the data further suggested that co-expression of both a receptor and ACSL4 was indicative of hormone-independent growth." (PMID 26636648, 2015). "Since the triple negative MDA-MB-231 breast cancer cells are sensitive to rosiglitazone, we also studied whether the inhibition of ACSL4 activity could reverse ER therapy resistance in cells that do not express ER." (PMID 26536660, 2015). "Additionally, we previously reported decreased XIST and AUTS2 mRNA expression in breast cancer cells as a result of forced ACSL4 expression." (PMID 26636648, 2015). "Despite evidence linking the action of ACSL4 to the development of various types of cancer including colon, hepatocellular carcinoma, prostate and breast cancer, very little is known regarding the signal transduction mechanism by which ACSL4 influences these lesions." (PMID 26536660, 2015). "Predictive value of ACSL4 as a marker for QNBC in breast cancer cell lines." (PMID 24155918, 2013). "In the case of breast cancer, however, ACSL4 has been demonstrated to increase production of lipoxygenase products, an effect attributed to increased uptake of AA-CoA into the mitochondria, followed by regeneration of free AA for subsequent conversion to prostaglandins." (PMID 24155918, 2013). "In breast cancer, this association is limited to the most aggressive forms of the disease, with the more benign, receptor positive cancers being negative for ACSL4 expression." (PMID 24155918, 2013). "Thus both substrate specificity and subcellular localization are currently under investigation in our laboratory in order to determine their role in mediating the effects of ACSL4 expression on breast cancer phenotype." (PMID 24155918, 2013). "We have presented evidence here that expression of a lipid metabolic enzyme, ACSL4, inversely correlates with the presence of steroid hormone and growth factor receptors in breast cancer, and as such may be a marker for the highly aggressive QNBC." (PMID 24155918, 2013). "Previous studies have demonstrated that ACSL4 is overexpressed in both liver and colon cancer as well as in aggressive forms of breast cancer, and it has been suggested that metabolism of AA may play a role in mediating the effects of ACSL4 expression." (PMID 24155918, 2013). "ACSL4 expression in steroid hormone/HER2 receptor positive breast cancer cell lines." (PMID 24155918, 2013). "Differential expression of ACSL4 in breast cancer as a function of receptor status." (PMID 24155918, 2013). "Thus ACSL4 serves as one of many biomarkers of an aggressive breast cancer phenotype and/or resistance to hormonal interventions." (PMID 24155918, 2013). "Therefore, the aim of this study was to use a tetracycline Tet-Off system of MCF-7 xenograft model of breast cancer to confirm the effect of ACSL4 overexpression on tumor growth in vivo." (PMID 22808264, 2012). "Therefore, the aim of this study was to use a tetracycline Tet-Off system of MCF-7 xenograft model of breast cancer to demonstrate the effect of ACSL4 overexpression on tumor growth in vivo." (PMID 22808264, 2012). "The in vivo xenograft model of breast cancer in which the expression of ACSL4 changes the cell’s potential for tumor formation, growth and development may be useful for testing novel targeted therapies." (PMID 22808264, 2012). "A breast cancer cell model comprising different cell lines with varying cell proliferation, invasive and metastatic behavior was used to investigate the possible effect of the differential expression of ACSL4 on the aggression phenotype." (PMID 21085606, 2010). "Furthermore, it is possible that successful inhibition of ACSL4 in breast cancer cells might render these cells more sensitive to other treatments, both hormone-based as well as non-specific chemotherapeutic regimens." (PMID 37306503, 2023).
breast cancer (continued). "Notably, ER itself can be regulated by ACSL4, as ER expressions were reduced in MCF-7 Tet-Off/ACSL4 and restored upon treatment with doxycycline, suggesting ACSL4 negatively controls ER expression and mechanistically determines ER status in breast cancer along with its dependency on oestradiol." (PMID 35448537, 2022). "Thus, ACSL4 may serve as a valuable biomarker for breast cancer as well as a target for therapy in the way of promoting ferroptosis and drug sensitivity." (PMID 35910359, 2022). "Specifically, the expression of ACSL4 is significantly upregulated in multiple types of cancer, including breast ER negative, colorectal, and prostate, while it becomes downregulated in other cancers (breast cancer ER positive, lung cancer and cervical cancer)." (PMID 35910359, 2022). "However, this discrepancy could have arisen from the use of different cancer subtypes among the different studies, indicating a subtype-specific role of ACSL4 related to breast cancer progression." (PMID 35448537, 2022). "Therefore, thiazolidinediones could be potential therapeutic agents in the treatment of breast cancer, a cancer type in which ACSL4 was found to play a role promoting its malignancy and chemoresistance." (PMID 35448537, 2022). "In addition, ACSL4 is considered a biomarker for liver and breast cancer." (PMID 33030783, 2020). "Therefore, the future joint study of ACSL4 and ERRα could lead to the design of new drug combinations for greater effectiveness in the treatment of highly aggressive breast cancer." (PMID 31311992, 2019). "Thus, whether or how CPT should reverse the resistance via inhibiting ACSL4‐mediated mTOR in breast cancer needs to be elucidated in the future work." (PMID 28272775, 2017). "Since forced expression of ACSL4 in breast cancer cells both increases COX-2 protein as well as production of PGE2, it has been suggested that a combinatorial approach of targeting both ACSL4 and COX-2 might comprise an effective therapy for more aggressive breast cancers." (PMID 28412757, 2017). "And, accordingly, designing effective combination therapies using ACSL4 and mTOR inhibitors together with agents targeting key molecular elements involved in breast cancer relies heavily on the identification of predictive markers that may provide the basis for patient therapy." (PMID 26536660, 2015). "In turn, sensitivity to rosiglitazone could be explained by the fact that MDA-MB-231 breast cancer cells express very high levels of ACSL4 and, as shown in the results above, ACSL4 affects the up and downregulators of mTOR and regulates mTORC1 and mTORC2 activities." (PMID 26536660, 2015). "Therefore, the in vivo xenograft model of breast cancer in which the expression of ACSL4 changes the cell’s potential for tumor formation, growth and development suggests that ACSL4 may be a novel therapy target." (PMID 22808264, 2012). "In lung adenocarcinoma and breast cancer, ACSL4 is considered a tumor suppressor, while in HCC and colon cancer, ACSL4 promotes tumor progression." (PMID 39984452, 2025). "In breast cancer, STAT3 promotes ferroptosis by increasing ACSL4 expression, while in ulcerative colitis (UC) cell models, STAT3 phosphorylation is downregulated, and the ferroptosis inhibitor Fer-1 can restore its phosphorylation." (PMID 40165005, 2025). "Instead of regulating MAPK pathways, we found that there is an interaction between MAP4K4 and ACSL4 that mediates radioresistance in breast cancer cells, with MAP4K4 acting as an upstream activator of ACSL4." (PMID 38548749, 2024). "In two breast cancer cell lines (MCF‐7 and T47D cells), estradiol augmented protein expression of ACSL4 by preventing its degradation via the proteasome." (PMID 39422319, 2024). "We proposed that ACSL4 promotes FAO and ATP production by upregulating CPT1A, thereby providing energy support for breast cancer metastasis." (PMID 38078907, 2023).
breast cancer (continued). "(B) The correlation between ACSL4 and ZEB2 mRNA expression in the TCGA cohort consisting of 1222 breast cancer patient samples." (PMID 38078907, 2023). "The expression levels of ACSL1, ACSL4, and ACSL5 are regulated by the estrogen receptor signaling pathway, and ACSL5 is a potential novel biomarker to predict the prognosis of breast cancer patients." (PMID 37746665, 2023). "(H) The correlation between ACSL4 and ZEB2 protein expression in the immunohistochemistry (IHC) cohort consisting of 45 breast cancer patient samples." (PMID 38078907, 2023). "ACSL4 and ZEB2 increase fatty acid oxygen consumption and promote adenosine triphosphate (ATP) generation in basal-like breast cancer (BLBC) cells." (PMID 38078907, 2023). "However, the mechanism by which ACSL4 regulates lipid metabolism in breast cancer remains unclear." (PMID 38078907, 2023). "However, regulation of lipid metabolism by ACSL4 during breast cancer invasion remains unclear." (PMID 38078907, 2023). "Consistently, tissue samples from 45 breast cancer patients had similar expression patterns, with ZEB2 and ACSL4 being relatively highly expressed in ER-negative patient samples (patients 6, 7, 8, and 9)." (PMID 38078907, 2023). "Taken together, these results indicate that ACSL4 and ZEB2 are correlated and overexpressed in highly invasive breast cancers." (PMID 38078907, 2023). "by using the TCGA database, we compared the overall survival between ACSL4 or ZEB2 high- and low-expression breast cancer patients." (PMID 38078907, 2023). "Experiments designed to either induce expression of ACSL4 in ACSL4-negative cells (MCF7 or SKBr3) or ablate expression in ACSL4-positive cells (MDA-MB-231) demonstrate a role for ACSL4 in stimulating proliferation, migration and invasion in breast cancer." (PMID 37306503, 2023). "(J) HE staining and IHC analysis of ACSL4, ZEB2, ERɑ expression in representative basal-like and luminal subtype breast cancer tissues." (PMID 38078907, 2023). "(G) Expression of ACSL4 and ZEB2 was analyzed by western blot in a panel of five breast cancer cell lines, including two basal-like (MAD-231, BT549), two luminal (T47D, MCF-7), and a Taxol-resistant cell lines." (PMID 38078907, 2023). "Another study on different types of breast cancers revealed that ACSL3 and ACSL4 were highly, but in a differential manner, expressed in a group of leiomyosarcomas, fibrosarcoma, and rhabdomyosarcomas." (PMID 36497375, 2022). "Notably, ACSL4 is preferentially expressed in basal-like breast cancer cell lines, promoting ferroptosis, while it is often silenced in most luminal-type breast cancer cell lines that are resistant to ferroptosis, suggesting that ACSL4 determines ferroptosis sensitivity in breast cancer." (PMID 33801564, 2021). "In vitro, expression of ACSL4 has been reported to be negatively correlated with ER, AR and HER2 in breast cancer cell lines." (PMID 33292585, 2020). "The interaction between ACSL4, LOXs and COX-2 regulated the proliferating and metastatic potential of breast cancer cells." (PMID 33292585, 2020). "The intracellular localisations of endogenously expressed ACSL3 and ACSL4 were further investigated by detailed subcellular fractionation analyses of HT1080 fibrosarcoma and MCF-7 breast cancer cells." (PMID 29450800, 2018). "ACSL4 mRNA is significantly overexpressed in TNBC and basal-like breast cancers, while ACSL3 mRNA expression predominates in RPBC and luminal and HER2-enriched subtypes." (PMID 28412757, 2017). "Moreover, as the expression of ACSL4 is negatively regulated by estrogen and in turn regulates the levels of ERα, the presence of ACSL4 could be a prognostic factor for hormone resistance in ERα-positive breast cancer tissues that begin to express it." (PMID 26536660, 2015).
breast cancer (continued). "Public databases were utilized to analyze the relationship between ACSL4 mRNA expression and the presence of steroid hormone and human epidermal growth factor receptor 2 (HER2) in both breast cancer cell lines and tissue samples." (PMID 24155918, 2013). "For that purpose, we used a xenograft model with which we examined the effect of inhibitors of ACSL4, LOX-5 and COX-2 on tumors formed after injection of MDA-MB-231 human breast cancer cells into nude mice." (PMID 22808264, 2012). "In previous studies, we have observed the same additive and inhibitory effect of a combination of ACSL4 and COX-2 inhibitors on cell proliferation of MDA-MB-231 breast cancer cells (unpublished data)." (PMID 22808264, 2012). "The results show that none of the employed combinations of two different inhibitors of ACSL4, LOX-5 and COX-2 produced a synergistic inhibition on cell proliferation and migration of MDA-MB-231 breast cancer cells." (PMID 22808264, 2012). "In contrast, inoculation of female athymic mice with the stable cell line MCF-7 Tet-Off/ACSL4 resulted in the development of mammary tumors, thereby demonstrating the transformational capacity of MCF-7 Tet-Off/ACSL4 cells." (PMID 22808264, 2012). "In this study, we showed that ACSL4 acts in combination with ACOT2, LOX and COX-2 to generate an aggressive phenotype in breast cancer cells." (PMID 21085606, 2010). "We then investigated the role of ACSL4 and ACOT2 in the production of lipooxygenase metabolites by disrupting the expression of endogenous ACSL4 and ACOT2 in MDA-MB-231 breast cancer cells." (PMID 21085606, 2010). "ACSL4 not only promotes the intracellular lipogenesis and lipid droplets accumulation but also enhances fatty acid oxidation and adenosine triphosphate production by upregulating CPT1A to drive breast cancer metastasis." (PMID 40050614, 2025). "The ACSL4 inhibitor PRGL493 inhibits cell proliferation and tumor growth in a breast cancer model." (PMID 40002245, 2025). "Additionally, ACSL4 and KLF4 are key molecules in the ferroptosis signaling pathway; they can inhibit ferroptosis in breast cancer cells while maintaining their malignant biological characteristics." (PMID 39664391, 2024). "In the present study, we demonstrate a novel positive feedback loop between the EMT transcription factor ZEB2 and the essential lipid metabolic enzyme ACSL4, resulting in enhanced cellular LDs accumulation and fatty acid oxidation (FAO) to drive breast cancer metastasis." (PMID 38078907, 2023). "As ACSL4 knockdown decreased CPT1A expression, we reasoned that ACSL4 might stimulate FAO in highly invasive breast cancer." (PMID 38078907, 2023). "This inverse relationship between ACSL4 and hormone receptor expression is not unique to breast cancer." (PMID 37306503, 2023). "Observational studies have demonstrated that ACSL4 mRNA expression is inversely correlated with ER, AR and HER2 expression in both breast cancer cell lines and tumor samples, and is most highly expressed in TNBCs that fall into the category of claudin-low and basal-like cancers." (PMID 37306503, 2023). "In conclusion, we provide insights into the mechanistic links between EMT and lipid metabolism and identify the ZEB2/ACSL4 axis as a novel metastatic metabolic pathway that stimulates both lipogenesis and FAO, resulting in enhanced breast cancer invasion and metastasis." (PMID 38078907, 2023). "Selaginella trichoclada-derived robustaflavone A induces ferroptosis by downregulating the expressions of acyl-CoA synthetase long-chain family member 4 (ACSL4), ACSL5, STEAP3, lysophosphatidylcholine acyltransferase (LPCAT3), and autophagy-related 7 (ATG7) genes in breast cancer cells." (PMID 36612314, 2023). "As we observed that depletion of ACSL4 greatly reduced cytoplasmic LDs abundance and invasive potential in BLBC cells, we hypothesized that LDs accumulation is an important step prior to breast cancer invasion." (PMID 38078907, 2023).